TERT (telomerase reverse transcriptase)
Diseases named in the same sentence as TERT in open-access papers (continued):
Sharing a sentence is not in itself a finding about the gene and the disease.
pulmonary fibrosis (continued). "The group established a progressive lung fibrosis model in TERT−/− TG mice by treating them with low doses of bleomycin (0.5 mg/kg) to closely recapitulate the molecular pathogenesis of clinical IPF, involving both continuous damage and telomere shortening." (PMID 31035374, 2019). "Its catalytic component, telomerase reverse transcriptase (TERT) is induced in lung fibroblasts from patients with fibrotic interstitial lung disease and in rodents with bleomycin-induced pulmonary fibrosis." (PMID 26555817, 2015). "Lungs seem to be one of the organs most sensitive to short telomere length and impaired telomere maintenance, with diseases such as idiopathic pulmonary fibrosis (IPF) and other lung pathology in the earliest generations of families with mutations in TERT." (PMID 25952108, 2015). "The impact of TERT deficiency in decreasing cell proliferation but increasing apoptosis rate in the collagen I-expressing MLF provides possible mechanisms for the impaired pulmonary fibrosis in TERT CKO animals." (PMID 26555817, 2015). "The findings in the current study revealed that it is the induced TERT/telomerase in mesenchymal cells that is important for BLM-induced pulmonary fibrosis." (PMID 26555817, 2015). "There are many candidate genes implicated in pulmonary fibrosis, such as IGF-I, IGFBPs, ELMOD2, TERT, TERC, SFTPC, SFTPA2), and MUC5B." (PMID 26447616, 2015). "Different studies in human and mouse models have attempted to provide biological insights into the association of TERT and TERC polymorphisms with pulmonary fibrosis." (PMID 24391588, 2013). "Our current findings parallel the recently reported association of loss-of-function TERT and TERC mutations with familial idiopathic pulmonary fibrosis." (PMID 19936245, 2009). "Over-expression of KLF4 in AECs could protect TERT expression and suppress the development of pulmonary fibrosis in bleomycin-induced mouse models." (PMID 35508454, 2022). "Our results showed that KLF4 could protect TERT expression in AECs by binding with the promoter of TERT, and may become a potential target for the treatment of pulmonary fibrosis." (PMID 35508454, 2022). "Additionally, the expression of TERT was down-regulated and P21 was up-regulated in bleomycin-induced pulmonary fibrosis model, compared with the control group." (PMID 35508454, 2022). "Overexpressing of KLF4 inhibited bleomycin-induced pulmonary fibrosis could protect TERT expression and telomere in AECs." (PMID 35508454, 2022). "Our study found that activation of KLF4 in AECs has a positive effect on the maintenance of TERT and telomere length, which may be a potential target for the treatment of pulmonary fibrosis." (PMID 35508454, 2022). "It has been reported that TERT could attenuate lung fibrosis via protecting alveolar epithelial cells against senescence." (PMID 33819185, 2021). "Emerging evidence supports that TERT could attenuate lung fibrosis via protecting alveolar epithelial cells against senescence." (PMID 33819185, 2021). "Importantly, half of the mice receiving TERT-expressing AAV9 showed undetectable lung fibrosis at 8 weeks post systemic viral administration, whereas all mice treated with an empty AAV9 vector showed severe fibrotic lesions." (PMID 31035374, 2019). "In addition, all subjects within this specific study who had a mutation in TERT or TERC and pulmonary fibrosis also had short telomeres." (PMID 28993806, 2017). "However the demonstration of selective mesenchymal cell TERT deficiency is unique to the current study and revealed for the first time the importance of TERT induction in this select cell population in pulmonary fibrosis." (PMID 26555817, 2015). "While DC is the most severe clinical manifestation of telomerase dysfunction, rare germline mutations in the telomerase genes (TERT and TERC) have also been found in patients with isolated aplastic anemia, myelodysplastic syndrome, acute myeloid leukemia, pulmonary fibrosis and liver cirrhosis." (PMID 23226558, 2012).
pulmonary fibrosis (continued). "Five subjects in this group carried mutations in TERT, two subjects had mutations in TERC, and one fulfilled clinical telomere syndrome criteria, a positive history of thrombocytopenia, a family history of pulmonary fibrosis, but no detectable mutation in TERT, TERC or DKC1." (PMID 31426295, 2019). "In addition, in IPF, 25% of individuals who have either familial or sporadic pulmonary fibrosis, without h-TERT or h-TERC mutation, have shorter telomeres in their circulating leukocytes." (PMID 24067943, 2013). "The results showed that AECs in bleomycin-induced pulmonary fibrosis model mice underwent senescent, and the expression of KLF4 and TERT was significantly decreased." (PMID 35508454, 2022). "Since the TERT mRNA level is elevated in BLM-induced pulmonary fibrosis, lung TERT expression was also evaluated in BLM-treated TERT fl/fl mice." (PMID 26555817, 2015). "We have previously shown that TERT is induced MLF and required for BLM-induced pulmonary fibrosis using TERT traditional KO mice." (PMID 26555817, 2015). "Investigations of familial IPF cases and their kindred identified germline mutations in the telomerase genes telomerase reverse transcriptase (TERT) and telomerase RNA component (TERC) in up to one-sixth of pulmonary fibrosis families." (PMID 26400796, 2015). "We previously demonstrated that telomerase and / or TERT are induced and required for BLM-induced pulmonary fibrosis, by comparing responses in TERT KO vs wild type mice." (PMID 26555817, 2015). "Genetic and molecular investigations indicate that telomere shortening induced by TERT disruption or telomere dysfunction without telomere shortening in AEC2 cells induces pulmonary fibrosis in mice." (PMID 34831112, 2021). "Furthermore, ChIP showed that KLF4 protein could bind to the TERT promoter region in MLE-12 cells, suggesting that KLF4 could implicate in pathogenesis of lung fibrosis through regulating TERT transcription in AECs." (PMID 35508454, 2022). "It is worth mentioning that IPF cases are usually seen in old age, and some relatives of IPF patients with both TERT or TERC mutations and telomere shortening do not develop pulmonary fibrosis, suggesting that aging and environmental factors are also involved in disease pathogenesis." (PMID 34859008, 2021). "Thus, in addition to their immunosuppressive activity, TERT and B7H3-dependent MDSC expansion/recruitment from BM could play a paracrine role to activate myofibroblast differentiation during pulmonary fibrosis with potential significance for disease progression mediated by sB7H3." (PMID 36045668, 2022). "Supporting the notion that TERT and TERC deficiency might contribute to pulmonary fibrosis by mechanisms dependent on telomerase activity but not necessarily telomere length, telomerase activity is induced in IPF and NSIP fibroblasts and systemic sclerosis lung compared to healthy donor samples." (PMID 24391588, 2013).
brain tumors (51 papers, 2014 to 2025). "As the WHO classification of brain tumors suggests analyzes for TERT promoter mutations predominantly in lesions with grade 2/3 borderline histology, we did not investigate benign meningiomas in our series." (PMID 37686690, 2023). "Mutations in the promoter of TERT commonly occur in diffuse gliomas but are also present in other types of brain tumors, such as pleomorphic xantoastrocytomas and ependymal tumors." (PMID 35693015, 2022). "Hypermethylation of the TERT promoter is associated with tumour progression during the transformation of paediatric brain tumours from low to high grade." (PMID 33802026, 2021). "The TERT mutation is a critical biomarker for brain tumors, and conventional methods may prove beneficial to some extent, with some limitations being that they are more expensive and take more time." (PMID 39940686, 2025). "They found that TERT promoter hypermethylation was positively correlated with TERT expression, and TERT promoter hypermethylation was associated with disease progression and poor prognosis in children with brain tumors." (PMID 37575241, 2023). "In addition, hypermethylation of specific CpG islands upstream of the TERT transcriptional start site have been associated with increased TERT expression and aggressive disease in both pediatric brain tumors and in adrenocortical carcinomas." (PMID 34549366, 2022). "Importantly, recent study showed that BRAF/TERT promoter double-mutated brain tumor cells were sensitive to YK-4-279 treatment, providing a therapeutic opportunity to manage brain tumor patients harboring both BRAF and TERT mutations." (PMID 34221969, 2021). "Epigenetic mechanisms can also regulate TERT expression, and this may have prognosis in certain pediatric brain tumors, where TERT promoter mutations are rare." (PMID 30967140, 2019). "Furthermore, it exhibits a positive association with high TERT expression levels and poor survival rates in patients with childhood brain tumors." (PMID 26575952, 2016). "The most extensively studied critical biomarkers in brain tumors include 1p/19q co-deletion, IDH isozyme mutation, MGMT methylation status, and TERT promoter mutation." (PMID 39940686, 2025). "Telomerase (TERT) is a major oncogene responsible for primary brain tumours, and its promoter mutation is found in approximately 80% of primary GBM cases, making TERT-derived peptides an ideal target for GBM neoantigen vaccines." (PMID 38183840, 2024). "The telomerase reverse transcriptase gene (TERT) is the most frequently altered gene in solid tumors, including brain tumors and GBM IDH-wildtype." (PMID 38201248, 2023). "Recently, we also used cis-X to validate ASE patterns for two genes (TERT and MYB) with SV-associated altered expression by SVExpress in a cohort of pediatric brain tumors." (PMID 33743584, 2021). "The UTSS region of the TERT promoter is partially or completely hypermethylated in malignant paediatric brain tumours, which express TERT, while normal brain tissues or low-grade tumours are unmethylated or hypomethylated." (PMID 33802026, 2021). "The 2016 WHO classification of diffuse LGGs heavily weighs molecular mutations classifying primary brain tumors with particular importance assigned to IDH mutation, 1p/19q co-deletion, ATRX mutation, TERT mutations, and MGMT methylation." (PMID 32111869, 2020). "Expression of the genes of the pre-replicative complex is anti-correlated with TERT expression both in human pediatric and in zebrafish juvenile brain tumors." (PMID 32331249, 2020). "By repressing TERT transcriptional activity, BP inhibits TA, an effect that is followed by human brain tumor cell senescence, such that the cells stay viable but stop synthesizing DNA and instead generate senescence-associated β-galactosidase." (PMID 30625996, 2019). "The patient’s resected brain tumor is BRAF V600E mutated, NRAS wild type (WT), and TERT C250T mutated." (PMID 26597176, 2015).
brain tumors (continued). "from the University of Toronto in Canada investigated whether TERT promoter methylation can be used as a biomarker of malignancy and a marker of prognosis in pediatric brain tumor patients." (PMID 37575241, 2023). "Meanwhile, eribulinmesylate, an FDA-approved drug for breast cancer and liposarcoma, has been shown to effectively and specifically inhibit the RNA-dependent RNA polymerase activity of TERT in multiple human GBM cell lines in preclinical mouse brain tumor models." (PMID 30625996, 2019). "In addition, a region located down-stream in the TERT promoter was investigated in paediatric brain tumors and found to be hypermethylated." (PMID 26870890, 2016). "Analysis of the mutational landscape of 19/40 tumors in the novel group using targeted next-generation sequencing revealed TERT promoter mutations (C228T) in two of the cases (online resource), with no other relevant events involving putative brain tumor genes." (PMID 34355256, 2021). "While histopathological grading was performed according to the current WHO classification of brain tumors in all cases, data about molecular alterations such as TERT mutations or DNA methylation were not available but have been shown to distinctly impact prognosis." (PMID 32809081, 2021). "Indeed, in other brain tumors and systemic cancers, epigenetic shifts in the TERT promoter regions including DNA methylation and histone modifications were reported to regulate TERT transcripts and reactivation, necessitating a rethinking of the mechanism to upregulate the expression of TERT." (PMID 29693015, 2018). "Thus, both in zebrafish brain tumor models and in human juvenile brain tumors, the expression of TERT is mostly anti-correlated with genes of the pre-replication complex, suggesting that in ALT tumors more active DNA replication may contribute to telomeric dysfunction." (PMID 32331249, 2020). "Although we found minimal changes in TERT or TERC (data not shown) expression in MST-312 treated brain tumour cells, which corroborate with the minimal effects of MST-312 in the TERT protein expression, we observed down-regulation in proteins reported to have roles in telomerase regulation." (PMID 25307264, 2014). "Even though we observed down-regulation in expression of MYC gene, the level of TERT protein and gene expression was not altered in MST-312 treated brain tumour cells." (PMID 25307264, 2014). "There were no significant changes in TERT and TR gene expression (data not shown) or TERT protein level following 1.0 μM MST-312 treatment for 48 hours.Next, we wanted to determine whether telomerase inhibition persists following withdrawal of MST-312 in brain tumour cells." (PMID 25307264, 2014).
lung adenocarcinoma (45 papers, 2010 to 2025). A carcinoma that arises from the lung and is characterized by the presence of malignant glandular epithelial cells. "It has been associated with multiple cancers, especially with lung adenocarcinoma, which is characterized by significantly increased TERT gene expression, telomerase activity and gene copy number." (PMID 33329574, 2020). "In the present study, we found Kras mutations increased TERT expression and telomerase activity and telomere length in both immortalized human bronchial epithelial cells and lung adenocarcinoma cells." (PMID 27329725, 2017). "A meta-analysis study showed that rs2853676 (TERT) was associated with an increased risk of lung adenocarcinoma in Caucasians population." (PMID 29299136, 2017). "We find patients with Kras mutations have higher TERT levels than those with wild-type Kras through examing the surgical specimens from lung adenocarcinoma patients." (PMID 27329725, 2017). "Previous studies indicated that the allele of rs2853677 in TERT, disrupted the Snail1 binding site, causing derepression of TERT transcription in response to Snail1 upregulation, was associated with a high risk of lung adenocarcinoma." (PMID 29299136, 2017). "Here, we confirmed that rs2853677, which is located in the second intron of TERT, is associated with a high risk of lung adenocarcinoma in the Han Chinese population." (PMID 27191258, 2016). "Here, we investigated these 6 previously reported risk loci and confirmed that rs2853677 in the second intron of the telomerase reverse transcriptase (TERT) gene is associated with a high risk of lung adenocarcinoma in the Han Chinese population." (PMID 27191258, 2016). "The high risk variant of rs2853677 disrupts the Snail1 binding site and derepresses TERT expression in response to Snail1 upregulation, thus increasing lung adenocarcinoma susceptibility." (PMID 27191258, 2016). "This difference in estimates between methods is eliminated after excluding the TERT SNP (rs2736100) that drives the heterogeneity in association estimates for lung adenocarcinoma." (PMID 26138067, 2015). "Even after dropping the three SNPs showing nominally significant (P < 0.05) association with lung adenocarcinoma (in TERT, OBFC1 and NAF1) the association is still significant (OR = 1.54, P = 0.018)." (PMID 26138067, 2015). "Second, the exclusion of the SNP in the TERT region from the SNP set used for lung adenocarcinoma resulted in a somewhat attenuated association, but the association remained statistically significant: (OR = 2.00, 95% CI 1.48, 2.70, P = 6.6 × 10−6)." (PMID 26138067, 2015). "A recent Japanese study also identified that TERT rs2853677 (European ancestry: r2 = 0.59) was associated with lung adenocarcinoma (p = 3.1×10–40)." (PMID 26042809, 2015). "Compared with an amplified TERT, those with an unamplified TERT had a 35% reduction (95% CI = 3%–56%) in risk of lung adenocarcinoma progression." (PMID 26497366, 2015). "Association was strongest in squamous-cell carcinomas and adenocarcinomas of the lung, where the 15p5.33/TERT locus is amplified at particularly high frequency." (PMID 24152305, 2013). "Some other reports demonstrated that anti-TERT siRNA can cause effective suppression of telomerase and to apoptosis in A549 lung adenocarcinoma cells." (PMID 23677713, 2013). "Among the 25 studies, many investigators also have established an association between the TERT rs2736100 polymorphism and risk of lung adenocarcinoma." (PMID 22221621, 2012). "The results show that TERT expression was different in lung adenocarcinoma (LUAD) samples, lung squamous cell carcinoma (LUSC) samples, and normal samples, and the expression level in LUAD or LUSC samples was higher than that in normal samples." (PMID 33905377, 2021). "TERT amplifications were frequent in ovarian cancer, adrenocorticol carcinoma, esophageal cancer, lung adenocarcinoma, and squamous cell carcinoma." (PMID 32121056, 2020).